IL4 (interleukin 4)
Diseases named in the same sentence as IL4 in open-access papers (continued):
Sharing a sentence is not in itself a finding about the gene and the disease.
parasitic infections (continued). "While we had a small sample size and non-significant seasonal comparisons, we detected a 15-fold increase in mean IL-4 signal in resampled animals while these animals were experiencing their highest GI parasite infection intensities, consistent with previous findings." (PMID 25388877, 2014). "Despite recent studies showing the importance of regulating IL-4Rα expression on CD4+ T cells following parasitic infection in vivo, only few studies have addressed how the cytokine receptors for IL-4/IL-13 are regulated on CD8+ T cells following virus infection in vivo." (PMID 23383283, 2013). "Studies on M2 activation in macrophages after parasitic infections show that IL-4 plays a central role in the expansion of this specific population of macrophages, through local proliferation, as opposed to M1 inflammation, which is characterised by influx of cells from the circulation." (PMID 23404620, 2013). "This was done to investigate the possibility that VV-WR infection induced IL-4 and/or IL-13 to up-regulate IL-4Rα expression on naïve bystander CD8+ T cells similar to what has been reported on naïve bystander CD4+ T cells responding to IL-4 following parasitic infection." (PMID 23383283, 2013). "In this study, we combined information on individual parasite infection intensities, immune-genetic constitution, and long-term parentage patterns to investigate a potential regulatory and functional role of IL4 SNPs on enteric parasite infections in a wild primate population." (PMID 21501512, 2011). "Indeed, dominated T helper type 2 responses in parasitic disease increased arginase expression by IL-4 and IL-13 signaling through the transcription factor STAT6." (PMID 21526166, 2011). "IL-4 is primarily produced by T helper 2 (Th2) cells and is instrumental in the activation of B lymphocytes and the subsequent production of antibodies, particularly immunoglobulin E (IgE), which is crucial in mediating responses to parasitic infections and allergic reactions." (PMID 40332240, 2025). "Among the hypothesised factors influencing the host immune system, the T helper cell 2 (Th2) response elicited by parasitic infections [including the increased production of interleukin-4 (IL-4), IL-13, and immunoglobulin E (IgE)] has been proposed to play an important role." (PMID 40999458, 2025). "By blocking the activity of IL-4/IL-13 receptors, dupilumab may potentially lead to parasitic infections for users because both cytokines contribute to the elimination of parasites through increased mucus production and eosinophilic mucosal inflammation in the gut." (PMID 39895989, 2024). "It was confirmed that cytokines such as IL-12, TNF-α, IFN-γ, and IL-2 play an important role in controlling the proliferation of Babesia in the early and acute stages of infection, while IL-10, IL-4, IL-5, and IL-6 may involve in chronic and low parasitemia stages of infections." (PMID 32733477, 2020). "It is well known that cytokines play an important role in the host immune response to parasite infection, and correspondingly the therapeutic effects of anti-parasite agents can be evaluated by monitoring the change of the serum cytokines level, e.g. the level of IL-4 in echinococcosis." (PMID 30642401, 2019). "The increase in IL-4 production in 11β-HSD1 deficient mice might thus indicate a greater or earlier polarisation to M2 macrophages, resulting in a less efficient parasite clearance and the observed increase in parasitemia." (PMID 29062028, 2017). "In addition, neutralization of IL-4 in IL-27Rα-deficient mice or inhibition of Arginase-1 in Ebi3-deficient mice was essential to control the parasitemia, but did not alter the host survival." (PMID 29033934, 2017). "At 8 d PI in baso IL-4/IL-13 (−) mice, FITC-dextran levels were positively correlated with parasitemia, plasma IL-1α, IFN-γ and IL-9, while bacterial 16S copies were positively correlated with plasma IFN-γ and IL-12p40." (PMID 38780542, 2024).
parasitic infections (continued). "The mean percentage of parasitemia, the mean survival time of the mice, the serum levels of IFN-γ, IL-4, IL-17, and TGF-β, and the effects of the SPE on the kidney, spleen, and liver tissues were investigated and compared across different treatment groups." (PMID 39830653, 2024). "Parasitemia remained directly and positively correlated with ileal MIP-1α and RANTES but was also newly and directly positively correlated with ileal KC, IL-4, and MIP-1β in the female network." (PMID 35970557, 2022). "16S copy numbers were also directly and weakly negatively correlated with plasma IL-4 and MCP-1, whereas parasitemia was directly and strongly positively correlated with plasma MIP-1α, and directly and weakly positively correlated with plasma IL-10." (PMID 35970557, 2022). "Similar to IL-4-dependent accumulation of lung ILC2 during parasite infection, skin ILC2 accumulation was dependent on basophil-derived IL-4 in the murine MC903-induced model of AD." (PMID 36846020, 2022). "In baso (+) mice, parasitemia was directly and weakly positively correlated with ileal MIP-1α, MIP-1β, MCP-1, and IL-4." (PMID 35970557, 2022). "The aim of this study was to measure the serum proinflammatory (IL-12, GM-CSF & IFN-γ) to anti-inflammatory (IL-10, IL-4) cytokine ratio, oxidant (MDA) level and antioxidant enzyme (SOD; GPx) activities after blood parasite infections." (PMID 34438696, 2021). "Upon parasite infection, levels of pro- and anti-inflammatory cytokines TNF-α, IFN-γ, IL-10, and IL-4 were increased by 7.0, 10.0, 14.0, and 1.5 times, respectively, in the systemic blood circulation of infected mice." (PMID 33803419, 2021). "At day 23 after the last inoculation, when the inflammation began to appear, we observed that LmJ3OE parasite infection led to a significantly lower mRNA induction of IL1-0, IL-4 and ARG1, and an mRNA increase of IL12p35 compared to LmMC parasites’ infection." (PMID 33114674, 2020). "Although the cytokines (IL-1β, IL-4, IL-6, IL-12, TNF-α, and IFN-γ) were increased in all groups after the parasite infection, the cytokine levels of the group immunized with SAG1-VLPs were markedly reduced compared to the non-immunized infection group." (PMID 32325746, 2020). "Previous studies had shown that parasitic infection with Nb induced the expression of AAM genes in Mac3+ macrophages in the lung suggesting that Mac3 (also known as CD107b and lysosomal-associated membrane protein 2, LAMP2) may also be induced by IL-4 and IL-13." (PMID 22292924, 2012). "Because M2-macrophage activation is mediated by IL-4 and/or IL-13 (Th2-type cytokines), these macrophages are normally associated with immune responses that possess a Th2-skewed cytokine environment, as observed in parasite infections and allergic inflammation." (PMID 21731741, 2011). "Later on, the IFN-γ to IL-4 ratio in PBS inoculated mice, decreased steadily, correlating with the decrease in ear thickness and in parasitemia at the inoculation site." (PMID 18060088, 2007). "Parasitemia was determined by the Brener method and relative gene expression (RGE) of six cytokines was evaluated by RT-qPCR to determine the Th1 response (IFN-γ, TNF-α, IL-1β, IL-12) and the Th2 response (IL-4 and IL-10)." (PMID 40743218, 2025). "Expression of CXCR5 and production of IL-4 are also not able to discriminate between Th2 and Tfh cells under parasite infection." (PMID 40391228, 2025). "In the study, the semipolar extract, both in combination and as a single agent, showed superior therapeutic effects in terms of parasitemia rate, percentage of parasite inhibition, histopathology, IFN-γ/IL-4, and IL-17/TGF-β balance compared to chloroquine alone." (PMID 39830653, 2024). "In the present study, we investigated the mean percentage of parasitemia, the mean survival time of the mice, the serum levels of IFN-γ, IL-4, IL-17, and TGF-β, and the effects of the SPE on the kidney, spleen, and liver tissues of mice across different treatment groups." (PMID 39830653, 2024).
parasitic infections (continued). "Of note, the perturbation of the liver damage parameters ALT, AST, total bilirubin, and also MDP values of IL-4, IL-6, IL-8, IL-12p70, CXCL9, CCL5, CCL2, CRP, fibrinogen and parasitemia levels showed an inverse correlation with the time living in the endemic area." (PMID 34727121, 2021). "The treatment of the WSX-1−/− mice with blocking anti-IL-4 antibody also reduces the T. cruzi parasite burden and also increases the number of IL-17+ CD4+ cells, indicating that IL-4 inhibits the Th17 cell development in parasitic infections." (PMID 32849534, 2020). "Surprisingly, we identified a unique CD4 T cell subset in the skin that was induced by both allergen priming in the skin and parasite infection in the lung that was committed solely to IL-13 expression and was completely independent of IL-4." (PMID 29910811, 2018). "We followed the number of IL-4- and IL-13-expressing CD4 T cells that appear in the draining lymph node and subsequent type 2 inflammatory response in the skin or lung following intradermal priming with allergen or parasite infection, respectively." (PMID 29910811, 2018). "For example, recent reports have shown that STAT6 phosphorylation on Tyr641 was induced by viral or parasitic infection independent of IL-4." (PMID 28099521, 2017). "The significant induction of IL-4 and IL-5 in the current study might reflect unknown cytokine functions in ECM development, which might be highlighted by nahG+ parasite infection." (PMID 26466097, 2015). "Rather, effective CD4+ T-cell help for B-cells, which can occur in the absence of IL-4, is required to control chronic parasitemia." (PMID 25628621, 2014). "The IL-4 level in HIV-infected individuals was generally higher than that in HIV-negative controls regardless of parasite infection status." (PMID 23971713, 2013). "Moreover, anti-IL-5 or anti-CD25, but not anti-IL-4, can abolish the beneficial effect of the parasitic infection." (PMID 35625566, 2022). "Interestingly, in both models the lack of T cell help did not seem to hamper parasitemia control, while the lack of Il-4 and the subsequent capacity to drive an IgG1 B cell differentiation pathway also did not affect parasitemia control." (PMID 32218784, 2020). "In baso IL-4/IL-13 (+) mice, FITC-dextran levels were positively correlated with MPO, NE, Mcpt1, and parasitemia in the main network, and bacterial 16S copies were negatively correlated with plasma IL-12p40, which was isolated from the main network." (PMID 38780542, 2024). "Patients with detectable parasitemia measured by RT-PCR in peripheral blood had a higher concentration of TNF-α, IL-1β, IL-4, and IL-6, whereas those with negative RT-PCR showed elevated levels of IL-17A." (PMID 38133693, 2023). "The deviation is exacerbated by the three mice that succumbed to parasitemia during the first peak and did not have the opportunity for Th2 type responses, mediated by IL10, IL13, IL4, and IL6 to develop." (PMID 35634275, 2022). "The beneficial effect of parasitic infection was abolished with an anti-IL-5 or an anti-CD25 monoclonal antibody (mAb), but not anti-IL-4 mAb." (PMID 29163523, 2017). "This study measured C-reactive protein, IL-4, and TNF-α levels to determine the inflammatory status of patients who showed elevated levels of C-reactive protein and TNF-α in diabetic patients with or without parasite infections." (PMID 39199338, 2024).
psoriasis (147 papers, 2007 to 2026). An autoimmune condition characterized by red, well-delineated plaques with silvery scales that are usually on the extensor surfaces and scalp. "Research on psoriasis susceptibility genes found that there is a 1.18-fold increase in loci related to IL-4/IL-13 signaling." (PMID 39859462, 2025). "AD is classically associated with dysregulation of the Th2 subset (IL-4, IL-5, IL-13, and IL-31), whereas the Th17 subset (IL-17, IL-21, and IL-22) has been implicated in the pathogenesis of psoriasis." (PMID 40535962, 2025). "On the other hand, although dupilumab, a dual inhibitor of IL-4 and IL-13 signaling, has been used successfully in BP, it is generally known to cause psoriasis." (PMID 38545121, 2024). "AD is strongly driven by helper type 2 T cells (TH2 cells) and is associated with IL-4 and IL-13 overproduction, whereas psoriasis is largely driven by TH17 cells and associated with IL-17 activation." (PMID 36271146, 2022). "Initial causative research has identified strong association between psoriasis and the interleukin genes (IL4, IL10, IL12B, IL13, and IL23R) in the northern European from US and UK." (PMID 24971308, 2014). "Polymorphisms in the Th2 cytokine genes IL-4 and IL-13have been reported in psoriasis, indicating that not only a dominant Th1/Th17 axis butalso a defective Th2 axis can affect the disease." (PMID 21611195, 2011). "Such an IL-4 variant could be of great interest to treat certain organ-specific autoimmune diseases, such as rheumatoid arthritis and psoriasis, by precisely controlling timing and location of activation without inducing systemic adverse side effects." (PMID 40561016, 2025). "Interestingly, associations of regions encoding Th2-related genes, particularly IL-4, IL-5, and IL-13, with the region of chromosome 5q31 containing multiple cytokine genes have also been found in patients with psoriasis." (PMID 29292715, 2017). "Our hypothesis was further strengthened by our observation that the ACD reaction was associated with an influx of Th2 cells, since IL-4 was shown to be an efficient psoriasis therapy." (PMID 25058585, 2014). "Finally there is a marginal association with psoriasis and different variants of a 370 kb region in which the IL-4, IL-5, and IRF-1 genes map." (PMID 23971052, 2013). "Since IL-4 and IL-13 are key mediators of Th2-mediated inflammation, their blockade by dupilumab may induce a shift from Th2-mediated inflammation to Th1/Th17 subsets, causing psoriasis." (PMID 39931435, 2024). "Moreover, decreased expression of filaggrin in the lesional skin of psoriasis due to secreted cytokines including IL-4, IL-13, IL-17, and TNF-α might increase the risk of skin cancer by increasing UV sensitivity of patients with psoriasis." (PMID 32987907, 2020). "Conversely, in AD, the emergence of psoriasis or psoriasiform eruptions has been reported, most notably with dupilumab, an IL-4/IL-13 inhibitor, and more recently with tralokinumab, a selective IL-13 inhibitor." (PMID 41542312, 2026). "The main cytokines involved in the pathogenesis of psoriasis are certainly TNFα, IL-12, IL-17, and IL-23, whereas in the pathogenesis of AD, IL-4, IL-13, and IL-31." (PMID 41481132, 2026). "It connects microbiome composition and function with systemic inflammation and cutaneous pathology, shaping disease-specific mechanisms such as Th2/IL-4/IL-13-mediated barrier dysfunction in AD and Th17/IL-23/IL-17-driven hyperproliferation in psoriasis." (PMID 41972685, 2026). "HSO were also treated with Th1 (TNF-α + IL-17) and Th2 (IL-4 + IL-13) cocktails inducing pro-psoriasis and pro-AD HSO changes, respectively." (PMID 41993536, 2026). "This case contributes to the current knowledge base for JAK inhibitors and suggests that patients who develop psoriasis on IL-4/IL-13 biologic therapy for AD can be treated safely and effectively with JAK inhibitors." (PMID 39906475, 2025).
psoriasis (continued). "Psoriasis primarily involves the TNF-α and the IL23-Th17-IL17 pathway, while AD is associated with a Th2 response driven by IL-4 and IL-13." (PMID 39859462, 2025). "While overproduction of IL-4 is an undesired element in atopic disease, IL-4 remains a potential treatment for autoimmune diseases such as psoriasis." (PMID 40561016, 2025). "They observed overlapping patterns of inflammation and keratinocyte activity between Blaschko linear psoriasis and psoriasis vulgaris but also detected notable differences, particularly in pathways related to IL-4, IL-13, and IL-36 signaling." (PMID 40539143, 2025). "skin dataset, we detected a positive enrichment of IL‐4 + IL‐13 signatures in AD and psoriasis compared to healthy controls." (PMID 40926620, 2025). "The pathogenesis of psoriasis and eczema is distinct—driven by T helper 17 (Th17) and Th1 T cells in the former and mediated by Th2 cells that produce interleukin 4 (IL-4), IL-5, and IL-13 in the latter." (PMID 38952860, 2024). "Monoclonal antibodies targeting the interleukin (IL)-4/IL-13 and the IL-17/IL-23 axes are available for the treatment of AD and psoriasis, respectively." (PMID 39161766, 2024). "In the case of the psoriasis model, a TH17-associated cytokine cocktail (IL-17A and IL-22) was used, and in the case of the AD model, a TH2-associated cytokine cocktail (IL-4, IL-5 and IL-13) was used." (PMID 38251799, 2024). "The markers IFN-γ, IL-13, IFN-γ/IL13, IL-17A/IL-13, IFN-γ/IL4, and IL-17A/IL-4 are representative of predicting the efficacy of psoriasis treatment." (PMID 38791078, 2024). "Rather than suppressing the immune system, the researchers attempted to achieve immune balance by using IL-4 and found improvements in psoriasis treatment outcomes." (PMID 38791078, 2024). "The biomarkers IFN-γ, IL-13, IFN-γ/IL4, IFN-γ/IL13, IL-17A/IL-4, and IL-17A/IL-13 are representative of the effectiveness of psoriasis treatment." (PMID 38791078, 2024). "The analysis demonstrated that schizandrin II directly influenced psoriasis-related proteins such as IL-4, IL-6, STAT3, and NFKBIA, while schizandrin A modulated the NFKBIA protein." (PMID 39590306, 2024). "Shifting the T cell differentiation toward Th2 by administering IL-4 has been shown to alleviate symptoms in patients with severe psoriasis." (PMID 38303723, 2024). "In AD, the predominant cytokines are IL-4, IL-5, and IL-13, and the pathogenesis differs from that of psoriasis." (PMID 39519167, 2024). "This is supported by the fact that, in clinical practice, the use of IL-17 inhibitors in the treatment of psoriasis can lead to AD and, conversely, the use of IL-4/13 inhibitors in the treatment of AD can lead to psoriasis-like skin rashes." (PMID 36834723, 2023). "Nevertheless, several studies also observed a significant increase in eosinophils and cytokines, such as IL-4, IL-5, IL-9, IL-31, and IL-33, among others, in the blood of patients with psoriasis." (PMID 36865550, 2023). "As a result, the IFN-γ/IL-4 ratio was higher in the psoriasis group than in the healthy group (P < 0.001)." (PMID 37596509, 2023). "In contrast, the serum concentrations of IL-4 were significantly lower in the psoriasis group than in the healthy group (P < 0.001)." (PMID 37596509, 2023). "We determined susceptibility of KC to VV and HSV-1 infection after exposure to representative cytokines prevalent in diverse inflammatory cutaneous diseases: IFNγ (lupus/AD; type 1), IL-4 and IL-13 (AD; type 2), IL-22 and IL-17A (psoriasis/AD, type 3)." (PMID 37298195, 2023). "Remarkably, IL-4 is a negative regulator of Th1 and Th17 cells, which can inhibit the secretion of IL-1b and IL-6 by psoriasis epidermal cells." (PMID 37408052, 2023). "Eosinophils are involved in type II immune response, which is related to T helper 2 cells and various interleukins (including IL-4, IL-5, IL-9, IL-13, IL-31, and IL-33, among others), differing from the IL-17/23 axis of psoriasis." (PMID 36865550, 2023).